VRK1 (VRK serine/threonine kinase 1)
Description:
Serine/threonine kinase involved in the regulation of key cellular processes including the cell cycle, nuclear condensation, transcription regulation, and DNA damage response. Controls chromatin organization and remodeling by mediating phosphorylation of histone H3 on 'Thr-4' and histone H2AX (H2aXT4ph). It also phosphorylates KAT5 in response to DNA damage, promoting KAT5 association with chromatin and histone acetyltransferase activity. Is involved in the regulation of cell cycle progression of neural progenitors, and is required for proper cortical neuronal migration (By similarity). Is involved in neurite elongation and branching in motor neurons, and has an essential role in Cajal bodies assembly, acting through COIL phosphorylation and the control of coilin degradation. Involved in Golgi disassembly during the cell cycle: following phosphorylation by PLK3 during mitosis, it is required to induce Golgi fragmentation. Phosphorylates BANF1: disrupts its ability to bind DNA, reduces its binding to LEM domain-containing proteins and causes its relocalization from the nucleus to the cytoplasm. Phosphorylates ATF2 which activates its transcriptional activity. Phosphorylates JUN.
Synonyms: HMNR10; PCH1; PCH1A
Tractability: Small molecule: a structure with a bound ligand is known; a high-quality ligand is known; it has a high-quality binding pocket; it belongs to a druggable protein family. PROTAC: UniProt records ubiquitination sites on it; ubiquitination databases record sites on it; its protein half-life has been measured; a small molecule that binds it is known.
Target class: Enzyme; CK1 protein kinase VRK family; Kinase; Protein Kinase; CK1 protein kinase group
Gene: Protein-coding gene on chromosome 14 (96,797,304 to 96,954,846, forward strand). Ensembl gene ENSG00000100749.
Subcellular location: Nucleus; Cytoplasm; Nucleus, Cajal body
Subcellular location (Human Protein Atlas): Nucleoplasm; Cytosol
Pathways (Reactome):
Cell Cycle: Initiation of Nuclear Envelope (NE) Reformation; Nuclear Envelope Breakdown
Gene Ontology:
Molecular function: histone binding; histone H2AX kinase activity; histone H3S10 kinase activity; histone H3T3 kinase activity; kinase activity; nucleosomal DNA binding; protein binding; protein kinase activity; protein kinase binding; protein serine kinase activity; protein serine/threonine kinase activity; ATP binding
Biological process: Cajal body organization; chromatin remodeling; DNA damage response; Golgi disassembly; neuron projection development; positive regulation of protein localization to chromatin; protein autophosphorylation; mitotic nuclear membrane disassembly; protein phosphorylation; regulation of neuron migration
Cellular component: Cajal body; chromatin; cytoplasm; cytosol; Golgi stack; nucleoplasm; nucleus
Genetic constraint (gnomAD): Loss-of-function variants: 31 observed, 55.99 expected, observed/expected ratio (o/e) 0.55, 90% interval 0.41 to 0.75. The upper end of that interval is the gene's LOEUF score, 0.75, which puts it in group 3 of 6, group 1 being the genes least tolerant of losing a copy. Missense variants: 392 observed, 476.29 expected, observed/expected ratio (o/e) 0.82, 90% interval 0.76 to 0.89. Synonymous variants: 133 observed, 148.27 expected, observed/expected ratio (o/e) 0.9, 90% interval 0.78 to 1.04.
Homologues: Orthologues: chimpanzee VRK1 (99% identical), macaque VRK1 (98% identical), dog VRK1 (90% identical), rabbit VRK1 (90% identical), pig VRK1 (90% identical), rat Vrk1 (88% identical), guinea pig VRK1 (88% identical), mouse Vrk1 (87% identical), tropical clawed frog vrk1 (68% identical), zebrafish vrk1 (62% identical), Drosophila melanogaster ball (39% identical), Caenorhabditis elegans vrk-1 (32% identical), and 63 more. Paralogues in human: VRK2 (47% identical), VRK3 (29% identical), CSNK1G3 (27% identical), CSNK1G1 (27% identical), CSNK1G2 (27% identical), CSNK1E (26% identical), CSNK1D (26% identical), CSNK1A1 (25% identical), TTBK2 (24% identical), CSNK1A1L (24% identical), TTBK1 (23% identical), CDC7 (17% identical).
Diseases named in the same sentence as VRK1 in open-access papers:
VRK1 is named in the same sentence as 92 diseases in open-access papers, as found by Europe PMC text mining. Sharing a sentence is not in itself a finding about the gene and the disease. The quoted sentences say what the papers report.
breast carcinoma (19 papers, 2010 to 2025). "VRK1 overexpression in the human kinome is linked to poor prognosis and heightened proliferation in aggressive breast cancer, especially in estrogen receptor-positive (ER+) tumors 47,57,58." (PMID 40384864, 2025). "For example, VRK1 is mutated or differentially expressed in glioma, breast cancer, and hepatocellular carcinoma and it regulates the progression of tumor development." (PMID 37547297, 2023). "VRK1 is also necessary for cell cycle entry and its loss results in a cell cycle arrest, infertility in mice or in a decreased proliferation of a xenograft model of breast cancer, indicating an important association of VRK1 with cell proliferation." (PMID 34067799, 2021). "Vaccinia-related kinase 1 (VRK1) belongs to a group of sixteen kinases associated to a poorer prognosis in human breast carcinomas, particularly in estrogen receptor positive cases based on gene expression arrays." (PMID 24731990, 2014). "They found that this circRNA is downregulated in breast cancer tissues and the expression level of circ‐VRK1 was associated with tumor size and TNM stage, and could be considered as an independent predictor of better overall survival." (PMID 34545638, 2021). "Finally, to address the association of VRK1 expression levels with human breast cancer and its progression, we assessed VRK1 protein expression in a custom tumor tissue microarray (TMA)." (PMID 30180179, 2018). "Indeed, an association of VRK1 overexpression with poor clinical outcome was observed in breast cancer patients with ER+ tumors of the luminal A subtype." (PMID 30180179, 2018). "VRK1 was identified as a protein whose expression is turned off in post-proliferative mature acini, prompting the hypothesis that elevated VRK1 expression might be associated with breast cancer progression." (PMID 30180179, 2018). "Moreover, the analysis of the human kinome in breast cancer cases led to the identification of a gene expression signature containing sixteen kinases that was associated with a poorer prognosis, and VRK1 was also present in this group." (PMID 24731990, 2014). "Indeed, high VRK1 expression shows a significant association with decreased relapse-free survival for patients with ER+ but not for ER- patients, indicating that VRK1 overexpression is correlated with poor prognosis in luminal breast cancers." (PMID 34067799, 2021). "VRK1-mediated MET might facilitate the colonization of distal sites by metastatic breast cancer cells, providing some insight into the frequent association of VRK1 overexpression with breast malignancies and the correlation between VRK1 overexpression and poor clinical outcome." (PMID 30180179, 2018). "Similar result was shown in breast cancer cell line and, more importantly, upregulating circ‐VRK1 suppressed cell proliferation and activated cell apoptosis in studied cell lines." (PMID 34545638, 2021). "circ-VRK1 is also one of the downregulated circRNAs in breast cancer, especially in breast cancer stem cells (BCSCs)." (PMID 30064463, 2018). "To complement our own IHC analysis of VRK1 overexpression in breast cancer patients, we took advantage of publically available repositories of transcriptomic and patient outcome data." (PMID 30180179, 2018). "Our analysis of human tumor tissue microarrays (TMAs) revealed that VRK1 protein levels are higher in lymph node metastases than in patient-matched mammary tumors." (PMID 30180179, 2018). "Strikingly, analysis of breast tissue microarrays (TMAs) indicates that VRK1 expression is higher in lymph node metastases than in patient-matched primary mammary tumors." (PMID 30180179, 2018). "Our IHC analyses of TMAs indicate that VRK1 protein levels are increased in lymph node metastases as compared to patient-matched primary mammary tumors." (PMID 30180179, 2018).
breast carcinoma (continued). "In breast cancer, VRK1 depletion inhibits tumor growth and metastasis and confers resistance to DNA-damaging agents, and it has been suggested that VRK1 is a potential therapeutic target and a prognostic marker for breast cancer." (PMID 26375549, 2015). "Receptor positive breast cancer has high levels of VRK1, a situation that has also been reported in other tumors such as head and neck squamous cell carcinomas, non-small lung cancer and high-grade astrocytomas." (PMID 24731990, 2014). "In this work we have validated that VRK1 protein is present at significantly higher levels in breast carcinomas that are positive for hormone receptors (estrogen and progesterone)." (PMID 24731990, 2014). "In experimental animal models, human breast cancer xenographs expressing high levels of VRK1 have a higher growth rate and invasive/dissemination potential." (PMID 24731990, 2014). "The level of VRK1 can regulate the ability of the cell to respond to DNA damage, which is a common mechanism to different types of therapy used in breast cancer." (PMID 24731990, 2014). "Based on this data we decided to study VRK1 protein expression in a panel of biopsies containing two groups of breast cancers, ER+/ERBB2- and ER-/ERBB2+." (PMID 24731990, 2014). "The level of VRK1 protein determines the sensitivity of breast cancer cells to DNA-damage based treatments, such as ionizing radiation or doxorubicin." (PMID 24731990, 2014). "For this aim it was first analyzed by immunohistochemistry the VRK1 protein level in normal breast and in one hundred and thirty six cases of human breast cancer." (PMID 24731990, 2014). "VRK1 protein was detected in normal breast and in breast carcinomas at high levels in ER and PR positive tumors." (PMID 24731990, 2014). "Next, to identify a mechanism that can link VRK1 to poorer prognosis, VRK1 was knocked-down in two breast cancer cell lines that were treated with ionizing radiation or doxorubicin, both inducing DNA damage." (PMID 24731990, 2014). "Different studies using RNA microarrays detected high levels of VRK1 expression in estrogen receptor positive breast cancer and at the same time the group with high VRK1 identified patients with a poorer prognosis." (PMID 24731990, 2014). "In breast cancer, overexpression of VRK1 can promote malignant progression of breast cancer cells." (PMID 38157278, 2023). "Another study on the expression of VRK1 in breast cancer showed the same conclusion." (PMID 36052378, 2022). "The expression of VRK1 directly affects the proliferation of breast cancer and liver cancer." (PMID 33718161, 2021). "Moreover, an effect of VRK1 on cellular motility has also been identified as contributing to breast cancer metastasis by facilitating mesenchymal to epithelial transition." (PMID 31527692, 2019). "To gain further insight into how VRK1 might contribute to breast cancer progression, we sought to determine how VRK1 overexpression might alter the cell biology of mammary epithelial cells." (PMID 30180179, 2018). "In addition, we used Oncomine’s online database to assess the upregulation of VRK1 mRNA in breast cancer." (PMID 30180179, 2018). "How might the induction of MET by VRK1 overexpression be relevant to breast cancer development or progression in vivo?" (PMID 30180179, 2018). "Mice engrafted with VRK1-depleted MDA-MB-231 breast cancer cells have been shown to develop fewer distal metastases than controls, suggesting VRK1 might play a role in cell migration, invasion, and/or colonization." (PMID 30180179, 2018). "To determine whether VRK1 overexpression is prognostic in breast cancer patients, we examined Kaplan-Meier ten year relapse-free survival curves for patients diagnosed with high-VRK1 expressing vs. low-VRK1-expressing cancers." (PMID 30180179, 2018). "VRK1 overexpression may facilitate breast cancer progression by enhancing the mesenchymal-to-epithelial (MET) transition thought to promote cancer cell colonization during metastatic spread." (PMID 30180179, 2018).
breast carcinoma (continued). "Taken together, our new insights into the influence of VRK1 on epithelial cell biology, and our assessment of VRK1 overexpression in patient samples, set the stage for future mechanistic studies into how VRK1 may modulate breast cancer progression." (PMID 30180179, 2018). "The underlying molecular base of this VRK1 biological effects suggest that a similar situation is very likely to occur in other types of cancers and is probably not restricted to breast cancer." (PMID 24731990, 2014). "First, it is reported that VRK1 gene expression could be selected as a significant prognostic indicator in the development of estrogen receptor-positive breast cancers." (PMID 25310002, 2014). "In conclusion high VRK1 levels can contribute to a poorer prognosis in breast cancer." (PMID 24731990, 2014). "The effect of VRK1 to protect against DNA damage was determined by studying the effect of its knockdown on the formation of DNA repair foci assembled on 53BP1 in response to treatment with ionizing radiation or doxorubicin in two breast cancer cell lines." (PMID 24731990, 2014). "The removal of VRK1 could be considered as part of a rescue mechanism, and defective induction of autophagy can contribute to genomic instability, as shown in a breast cancer model." (PMID 21386980, 2011). "VRK1 has been identified as a drugable kinase in rhabdomyosarcoma and breast cancer." (PMID 21829721, 2011). "Previously, VRK1 had not been associated with all of these cancers even though it is part of the signature depicting poor survival of luminal breast cancer patients." (PMID 21151926, 2010). "The implication of VRK1 in DDR suggests that it may produce tumor resistance to DNA damaged-based therapies which is consistent with its association to a poor clinical outcome in ER+ breast cancer." (PMID 34067799, 2021). "How might VRK1-induced MET contribute to breast cancer progression?" (PMID 30180179, 2018). "In accordance to this, it was found that the expression of VRK1 was preferentially expressed in the proliferation area in head and neck squamous cell carcinoma patients, and various authors have highlighted its potential role as a poor-outcome biomarker in human breast carcinomas." (PMID 27456229, 2016). "Moreover, we provided evidence about VRK1 biological significance in human breast cancer cell lines, since this kinase contributes to cell protection against DNA damage induced by therapy, and this function can be relevant for conferring a poorer prognosis to breast cancer cases." (PMID 24731990, 2014). "The development of highly specific VRK1 inhibitors might be of potential clinical use in those cancers where these kinases identify a clinical subtype with a poorer prognosis, as is the case of VRK1 in breast cancer." (PMID 21829721, 2011). "For example, a mitosis related kinase gene VRK1 was found to be active in many hematological tissues as well as in the many tumors of connective and muscular tissues (sarcomas, head & neck and melanoma) and in most gynecological cancers (uterine, ovarian and breast cancers)." (PMID 21151926, 2010). "Consistent with that finding, VRK1 depletion was previously shown to suppress cell proliferation in WS1 fibroblastic cells and lung cancer cells, and to reduce tumor size in breast cancer in vivo." (PMID 26375549, 2015). "The expression of VRK1 and VRK2 as well as estrogen receptor and ERBB2 were determined in a panel of eight human breast cancer cell lines, including four of each type, luminal or basal." (PMID 24731990, 2014). "This role of VRK1 in DNA-damage response is in agreement with the predictive role of 53BP1 and BRCA1 expression in breast cancer." (PMID 24731990, 2014). "This suggests that knockdown of VRK1 may lead to an increased level of apoptosis in LUSC, and it has also been previously shown that VRK1 can promote apoptosis in breast cancer cells and posttransplant cardiomyocytes." (PMID 37547297, 2023).
breast carcinoma (continued). "Also, VRK1 functions as a coordinator of several processes required for cell division, identifies a bad prognosis signature in breast cancer, and specific expression patterns in human tissues, normal and malignant." (PMID 21829721, 2011). "Moreover, several studies have suggested the involvement of VRK1 overexpression and its correlation with poor prognosis in many cancer types such as head and neck squamous cell carcinoma (HNSCC), lung cancer, hepatocellular carcinoma (HCC), esophageal cancer, glioma or breast cancer." (PMID 34067799, 2021).